TNF (tumor necrosis factor)
Diseases named in the same sentence as TNF in open-access papers (continued):
Sharing a sentence is not in itself a finding about the gene and the disease.
Arrhythmia (continued). "We aimed to investigate whether early post-PVI levels of C-reactive protein (CRP), white blood cells, tumour necrosis factor alpha (TNF-α) and transforming growth factor beta 1 (TGF-ß1) are associated with long-term arrhythmia recurrence." (PMID 40507635, 2025). "Large national data show no increased arrhythmia risk with anti-TNF; long-term findings support cardiovascular safety." (PMID 41552252, 2025). "Given that cytokines such as TNF-α, IL-1, and IL-6 contribute significantly to myocardial remodeling, ion channel dysfunction, oxidative stress, and autonomic dysregulation, targeting these pathways offers promising avenues for arrhythmia treatment." (PMID 40901119, 2025). "Also, mice with TNF knockout or treated with an anti-TNF antibody who had undergone ischemia/reperfusion displayed a decreased infarct area in the LV, less arrhythmia, less NF-κB activation, and a reduction in cytokine expression." (PMID 36816471, 2023). "TNF-α rapidly increased spontaneous calcium release activity in mouse atrial cells via the mitochondrial reactive oxygen species pathway and promoted the possibility of arrhythmia-triggered activity." (PMID 36059969, 2022). "In our study, we found that the "inflammatory cytokines milieu" (in our study defined as elevated IL-18, sIL-2Rα and TNF-α) of permanent AF subjects is significantly associated with arrhythmia but not with an underlying cardiovascular disease." (PMID 32364529, 2020). "Interleukin-6, tumor necrosis factor-alpha, and other cytokines released after rituximab use may lead to cardiac arrhythmias, vasoconstriction, platelet activation, and/or rupture of atherosclerotic plaque." (PMID 25023062, 2014). "The aim of this study was to investigate early post-PVI levels of inflammatory biomarkers, including CRP, neutrophils (Neu), leukocytes (Lkc), TNF-α and TGF-ß1, as potential predictors of arrhythmia recurrence." (PMID 40507635, 2025). "In this context, we also identified an increased expression of TNF-α in the Sed CCC group, which potentially favored the development of arrhythmias." (PMID 40356773, 2025). "Conversely, tumour necrosis factor alpha (TNF-α) levels have shown a correlation with left atrial diameter (LAD), but no clear association with arrhythmia recurrence." (PMID 40507635, 2025). "TNF-α has been demonstrated to participate in myocardial IR by promoting leukocyte infiltration of the myocardium, while TNF-α knockout mice have decreased arrhythmia and improved cardiac function during reperfusion." (PMID 35425785, 2022).
gingivitis (52 papers, 2014 to 2025). A disorder involving inflammation of the gums; may affect surrounding and supporting structures of the teeth. "Meanwhile, the IL-1RN*2 allele (A2) and TNF-α (−308G/A) polymorphisms were suggested to be protective against gingivitis." (PMID 41300760, 2025). "In another study, the gene polymorphism of TNF-α was identified as protective factor against gingivitis." (PMID 41300760, 2025). "This study analyzed the correlation between TNF-α (−308 G/A) polymorphism and gingivitis, and serum- and salivary-TNF-α concentrations, in a cohort of Mexican individuals." (PMID 41300760, 2025). "Other studies have investigated the role of other salivary cytokines, such as tumor necrosis factor-alpha (TNFα) and interleukin-8 (IL-8), which are also involved in the immune response and contribute to the inflammatory process associated with caries and gingivitis." (PMID 39358612, 2024). "During gingivitis, there is an increase in the cellular production of pro-inflammatory cytokines, such as interleukin (IL)-1β, tumor necrosis factor-alpha (TNF-α), and IL-6, which contribute to tissue destruction and disease progression." (PMID 40867800, 2025). "They made an ointment cream and tested it on an animal model of gingivitis by looking at gene expression of NF-κB, IL-1β, IL-6, p38, and TNF-α." (PMID 38978754, 2024). "Serum/plasma IL-β, IL-6, and TNF-α have been suggested to be elevated in individuals with both PD/gingivitis and T2DM compared to the PD+ T2DM−, PD− T2DM+, or PD− T2DM− groups." (PMID 37893143, 2023). "A gel preparation of Eug-NE was studied as an anti-inflammatory, analgesic, and anesthetic in treating induced gingivitis in rats and showed significant results by reducing tumor necrosis factor-α (TNF-α) and IL-1β." (PMID 37235301, 2023). "The expression of proinflammatory markers such as TNF-α, IL-6, IL-8, IL-17, and IL-1β has been reported to be detected in the gingival crevicular fluid after gingivitis and can also be detected in saliva." (PMID 36998066, 2023). "The increased gingival crevicular fluid (GCF) TNF-α in DM1 children with gingivitis confirms that TNF-α is closely related to gingival inflammation." (PMID 36769794, 2023). "In contrast, DMN patients with gingivitis showed a trend in higher levels of IL-10, TNF-α, IgA and NF-κB while α-amylase was lower." (PMID 35788667, 2022). "While other analytes were not significant amongst the sub-groups, there was a trend of lower α-amylase, higher IL-10, IgA, and TNF-α in the DMN with gingivitis group as compared to DMN with healthy periodontium." (PMID 35788667, 2022). "Zhang’s group (2013) investigated alterations in DNA methylation of the TNF promotor in gingival biopsies from CP, experimentally induced gingivitis, and healthy controls." (PMID 32867386, 2020). "The authors demonstrated that the TNF promotor was hypermethylated in CP compared to controls, but was not modified at either the induction or resolution phase of experimental gingivitis." (PMID 32867386, 2020). "Gingivitis is a pathologic response to microbial byproducts, leading to proinflammatory cytokines such as interleukin (IL)-1, IL-6, and IL-8, tumor necrosis factor (TNF), and the like, that leads to the destruction of the periodontium." (PMID 32064220, 2020). "The objective of this study is to evaluate the salivary concentrations of IL-1β, IL-6, IL-8, IL-10, TNFα and IL-12p70 of DS individuals and compare to cerebral palsy (CP) and normoactive patients (all with gingivitis)." (PMID 32509226, 2020). "This study also found that TNFα in crevicular fluid was greater in patients with gingivitis than in the control group." (PMID 24790719, 2014). "Additionally, gingivitis was significantly associated with CTRP-1 and TNF-α (p = 0.004 and p < 0.001, respectively)." (PMID 40542868, 2025).
gingivitis (continued). "Interestingly, in a previous study, the same probiotics did not have an effect on salivary levels of a battery of inflammatory markers including interleukin 1β and tumor necrosis factor α in patients with gingivitis." (PMID 33805894, 2021). "The hypothesis of the study was that individuals with DS present higher levels of IL-1β, IL-6, IL-8, IL-10, TNFα and the p70 subunit of interleukin-12 (IL-12p70) cytokines when compared to individuals with CP and normoactive, all with gingivitis." (PMID 32509226, 2020). "However, to our knowledge, our study is the first to include histological assay results when reporting the effects of omega-3 supplementation on experimental gingivitis biomarkers (IL-1β, TNF-α)." (PMID 24711890, 2014). "The study demonstrated that TNF-α (−308G/A) polymorphism is protective in individuals who carry the A/A genotype and allele A. The G/A genotype correlates with augmented concentrations of high-density lipoprotein cholesterol (HDL-C) in the group of gingivitis patients." (PMID 41300760, 2025). "Thus, it was proven that the TNF-α −308A/A genotype is protective against gingivitis." (PMID 41300760, 2025). "Therefore, in order to be able to discover whether there is a relationship between TNFα and inflammation in gingivitis further studies are required with groups of similar ages." (PMID 24790719, 2014). "Clinical interventions for severe gingivitis have demonstrated reductions in oral TNF-α and CRP, while advanced gingivitis also correlates with elevated IL-1β in saliva." (PMID 40558433, 2025). "We also found that TNFα was downregulated in T1DM patients, reaching statistical significance only in those with gingivitis." (PMID 41280935, 2025). "The gingivitis subgroups showed a significantly higher PI, GI, PPD, GCF volume, and TNF-α total amounts than the healthy subgroups (p < 0.0001)." (PMID 36769794, 2023). "Finally, gingivitis produced changes in saliva, with salivary levels of GM-CSF, IL-6, IL-7, IL-15, IP-10, KC-like, IL-10, IL-18, MCP1, TNFα being statistically significantly higher in the saliva of CG2 dogs compared to CG1." (PMID 38521919, 2024). "In healthy controls, increased concentrations of salivary-TNF-α and -HDL-C, and higher flow of saliva were registered; meanwhile, triglycerides, low-density lipoprotein cholesterol, and very low-density lipoprotein cholesterol concentrations were augmented in the group of gingivitis patients." (PMID 41300760, 2025). "In samples from nonpregnant women, GCF TNF-α level could not be classified as a marker of inflammation in gingivitis." (PMID 27034591, 2016). "Unlike in GCF, salivary TNFα and IFNγ were elevated in T1DM across all periodontal statuses, with significant increases in gingivitis (TNF-α, p < 0.0001) and healthy (IFNγ, p < 0.05) groups." (PMID 41280935, 2025).
hypothyroidism (52 papers, 2011 to 2025). Abnormally low levels of thyroid hormone. "One is by the development of (sub)clinical hypothyroidism (TAI is the most frequent cause of hypothyroidism) and another via inflammatory pathways involving IL-6 and TNF-α; both pathways can lead to insulin resistance (IR)." (PMID 35195084, 2022). "The association of hypothyroidism with plasma pro-inflammatory markers such as TNF-α and CRP has been demonstrated in some studies." (PMID 25333636, 2014). "The inflammatory signs observed in patients with hypothyroidism are thought to be related to the interplay between IL-6, TNF-α, and IL-1, which may be linked to elevated levels of HCRP during hypothyroidism." (PMID 39600704, 2024). "TSH, TPOAb, CRP, percentage of Th17 cells, Th17/Treg ratio, IL-2, IL-6, IL-10 and TNFα levels increased significantly in the hypothyroidism group compared to the control group, and FT4 levels and percentage of Treg cells decreased significantly." (PMID 41573549, 2025). "We found that CRP, IL-2, IL-6 and TNF-α levels were increased in pregnant women with hypothyroidism in the first half of pregnancy." (PMID 41573549, 2025). "Serum levels of TNF-α and interleukin-2 (IL-2) were found to be considerably greater in pregnant women with hypothyroidism than in normal healthy women." (PMID 40237055, 2025). "The serum CRP, IL-2, IL-4, IL-10 and TNF-α levels in the hypothyroidism group were greater than those in the control group (P < 0.05)." (PMID 39185088, 2024). "For instance, the administration of T3 normalized the increased expression of the pro-inflammatory cytokines IL-1β, IL-6, and TNF-α in the hippocampus of rats with hypothyroidism." (PMID 39513900, 2024). "We found that the CRP, IL-2, IL-4, IL-10, and TNF-α levels were greater in the hypothyroidism group than in the control group." (PMID 39185088, 2024). "Hypericum perforatum’s extract, like the antidepressants Milancipran and Agomelatin, decreased serum levels of cortisol and TNF-α, as well as depressive-like behavior in rats subjected to a subclinical hypothyroidism model." (PMID 37687297, 2023). "Other hypotheses may be reduced clearance of inflammatory cytokines such as TNF-alpha and IL-1, which leads to a decrease in the level of 1 5'-deiodinase, which again leads to decreased peripheral conversion of T4 to T3, which again causes low T3 levels causing hypothyroidism." (PMID 37602030, 2023). "Numerous investigations have discovered that increased disease activity in RA patients and blood tumor necrosis factor-α levels have an effect on hypothyroidism." (PMID 37600807, 2023). "The hypothyroidism group had higher serum IL-2, TNF-α, and IFN-γ levels, and lower IL-10 levels, than the control group." (PMID 37051293, 2023). "In a previous study, the levels of TNF-α, IL-6, and other cytokines increased in hypothyroidism rats." (PMID 36514041, 2022). "A previous study showed that hypothyroidism rats had increased levels of TNF-α, IL-6, and other cytokines." (PMID 36514041, 2022). "In this study, we found that the levels of hsCRP, IL-10, IL-6 and TNF-α in pregnant women with clinical hypothyroidism during pregnancy were significantly higher than those in the control group." (PMID 36275023, 2022). "Common drugs used to treat RA, such as glucocorticoids and leflunomide, interfere with thyroid function, whereas tumor necrosis factor inhibitors improve thyroid function in RA patients with hypothyroidism." (PMID 36313752, 2022). "Some studies have reported that chemerin and TNF-α levels were comparable between sHT and the control groups, but levels of these markers were significantly increased in hypothyroidism patients." (PMID 29440225, 2018).
hypothyroidism (continued). "Thyroid infiltrating lymphocytes (TIL) in hypothyroidism is a reliable source of TNF-α." (PMID 40672362, 2025). "Additionally, hs-CRP, IL-2, IL-6 and TNF-α levels were elevated in the hypothyroidism group, suggesting an inflammatory response in these patients during the first half of pregnancy, aligning with previous studies." (PMID 40443669, 2025). "Though this is one study, TNFα elevation in patients with hypothyroidism may be a driver in the development of SWD within this patient group." (PMID 40416190, 2025). "Patients with hypothyroidism or hyperthyroidism have been shown to have high plasma TNF-α levels." (PMID 39273664, 2024). "Conversely, when we treated hypothyroidism as an exposure factor, we detected a causal association between hypothyroidism and 13 inflammatory cytokines (IL-13, IL-16, IL-2rα, IL-6, IL-7, IL-9, G-CSF, SCGF-β, IP-10, MIG, MIP-1β, SDF-1α, and TNF-α)." (PMID 38317717, 2023). "TPOAb may aggravate the thyroid injury process by enhancing the production of TNF-α, thereby affecting thyroid function and leading to hypothyroidism." (PMID 37051293, 2023). "The levels of hsCRP, IL-6 and TNF-α in SIBO-positive pregnant women with clinical hypothyroidism after treatment with probiotics combined with prebiotics were significantly lower than before treatment, and the concentrations of TC and LDL were also lower after treatment." (PMID 36275023, 2022). "Unlike the severity of hypothyroidism, the development of HT itself was associated with C allele of tumor necrosis factor (TNF)-α -1031T/C SNP." (PMID 22654557, 2011). "Second, Th1 cytokines (e.g., IFN-γ, TNF-α) mediate thyroid follicular cell apoptosis, triggering transient thyrotoxicosis, followed by Hashimoto-like pathology with elevated thyroid peroxidase antibodies (TPOAb), ultimately progressing to permanent hypothyroidism." (PMID 40264768, 2025). "This initiates the production of further proinflammatory cytokines, such as TNF-α, that may be involved in hypothyroidism in pregnancy through stimulation of the nuclear factor-κB signaling pathway that extensively damages thyroid cells, affects apoptosis, and alters the immune status." (PMID 41573549, 2025). "The study with 91 patients with HT (42 with hypothyroidism and 49 euthyroidism) and 50 healthy people found that the levels of inflammatory factors, including interleukin 6 (IL-6), 12, 10 and tumor necrosis factor-α (TNF-α) were lower in the control group compared to the HT group." (PMID 35743024, 2022). "Furthermore, Th1 cytokines (such as IFN-γ and TNF-α) induce apoptosis of thyroid follicular cells, triggering transient thyroiditis with elevated thyroid peroxidase antibodies (TPOAb), which may eventually progress to permanent hypothyroidism." (PMID 40894206, 2025). "Hypothyroidism patients had increased C-reactive protein (CRP), interleukin-2 (IL-2), IL-4, IL-10, and tumor necrosis factor (TNF)-α levels." (PMID 39185088, 2024). "The serum levels of IL-2, TNF-α, and IFN-γ in the hypothyroidism group were significantly increased (p < 0.01, p < 0.001, p < 0.001, respectively), whereas the level of IL-10 was dramatically reduced (p < 0.001), compared to those in the control group." (PMID 37051293, 2023). "In the present study, serum IL-2, TNF-α, and IFN-γ levels were significantly increased in the hypothyroidism group compared to those in the control group." (PMID 37051293, 2023). "The levels of TSH, hsCRP, IL-10, IL-6, TNF-α, TC, LDL, FFA and ApoB in the pregnancy hypothyroidism group were higher than those in the control group (P <0.05)." (PMID 36275023, 2022).
hypothyroidism (continued). "Th1 cytokines, such as interferon (IFN)γ, interleukin (IL)-1α, IL-1β, Il-2, tumor necrosis factor (TNF)-α, and TNF-β, trigger thyrocyte destruction by CD8+ cytotoxic cells, which ultimately leads to gland atrophy and hypothyroidism." (PMID 33916948, 2021). "Hypothyroidism resulted in significant increases in the plasma inflammatory markers CRP and TNF-α and IL6, whereas reversing the hypothyroid state further increased these levels." (PMID 25333636, 2014). "In animals with hypothyroidism, rutabaga sprouts enhanced the negative effect of iodine deficiency or sulfadimethoxine ingestion on the organism by increasing the WBC (RDI), TNF-α (RS), creatinine (RS), and triglyceride (RDI and RS) levels, as well as decreasing PLT (RS) level." (PMID 30927245, 2020). "In animals with hypothyroidism, rutabaga sprouts enhanced the negative effect of iodine deficiency and sulfadimethoxine ingestion on the organism by either increasing WBC (RDI), TNF-α (RS), creatinine (RS), and triglyceride (RDI and RS), or decreasing PLT (RS) and the body temperature (RDI and RS)." (PMID 30927245, 2020).